THBS2 (thrombospondin 2)
Diseases named in the same sentence as THBS2 in open-access papers (continued):
Sharing a sentence is not in itself a finding about the gene and the disease.
cancer (continued). "In addition to promoting angiogenesis via PI3K/AKT activation, THBS2-expressing cancer-associated fibroblasts have been identified as drivers of oxaliplatin resistance through the secretion of COL8A1, which activates PI3K/AKT signalling and induces epithelial–mesenchymal transition." (PMID 40860666, 2025). "Notably, THBS2 was highly associated with the transformation and pro-cancer activity of CAFs." (PMID 38827236, 2024). "In addition, THBS2 expression was positively associated with angiogenesis and epithelial–mesenchymal transition and negatively associated with DNA repair, cell cycle and DNA replication in most cancer types." (PMID 37884956, 2023). "Determining the THBS2 concentration in body fluids is a potentially important tool for cancer screening due to the overexpression of THBS2 in various cancers." (PMID 40141965, 2025). "TGFB1 from cancer cells activated CAFs to produce THBS2 through the p-Smad2/3 pathway, suggesting an important role for TGFB association with THBS2 in cancer progression." (PMID 41373732, 2025). "Its relevance to a wide variety of diseases makes THBS2 a potential cornerstone biomarker for not only prognostic evaluation but also early cancer screening." (PMID 40141965, 2025). "In this research field, we recently found that the matricellular proteins thrombospondin 1 (THBS1) and 2 (THBS2) are highly expressed and released in the extracellular fluid (ECF) of the iCCA TME from cancer-associated fibroblasts (CAFs)." (PMID 38339060, 2024). "This study found that THBS2 is positively associated with CAF activation, epithelial-mesenchymal transition (EMT), and chemoresistance at the pan-cancer level." (PMID 39732719, 2024). "EGFR and Wnt/β-catenin signaling are two of the pathways implicated in the oncogenesis and cancer progression induced by both THBS1 and THBS2, as well as in the activation of the EMT program." (PMID 38339060, 2024). "THBS2 expression in pan-cancer tissues and cell lines was assessed using the HPA, TISCH and CCLE databases." (PMID 37884956, 2023). "Univariate Cox analysis was performed to examine the relationship between THBS2 expression and prognosis in pan-cancer based on OS, DSS, DFI and PFI data." (PMID 37884956, 2023). "The difference in THBS2 expression in GC tissue was consistent with results that reported a vital role for the ECM receptor interaction pathway in cancer progression." (PMID 37361568, 2023). "In this study, we compared the expression of THBS2 across various cancer types (pan-cancer analysis) and examined its relationship with the immune microenvironment, genomic mutations, methylation status and prognosis." (PMID 37884956, 2023). "Radar plots was generated to demonstrate the correlation between IPSs and THBS2 expression in pan-cancer." (PMID 37884956, 2023). "Among the cells exhibiting more significant THBS2 expression (log[TPM/10 + 1] > 1), fibroblasts had remarkably high expression of THBS2 in most cancers." (PMID 37884956, 2023). "Among all thrombospondins, THBS2 has been most commonly studied in cancer diagnosis and progression." (PMID 36405394, 2022). "Our results showed that THBS2 expression positively correlated with ImmuneScore and StromalScore in 30 and 19 cancer types, respectively." (PMID 35701829, 2022). "Our analysis of TCGA and GTEx database data revealed the abnormal expression of THBS2 in 17 types of cancer relative to that in healthy tissues." (PMID 35701829, 2022). "The results indicated that THBS2 expression was significantly higher in 17 cancers, mainly in BRCA, PAAD, and SARC, and significantly lower in 14 cancers, especially CESC, UCEC, and UCS." (PMID 35701829, 2022). "Overall, our findings indicated that THBS2 overexpression correlates with a poor prognosis and increased immune cell infiltration in numerous cancer types." (PMID 35701829, 2022). "We further analyzed THBS2 mRNA expression in GC and cancer-adjacent tissues RNA sequencing data from GSE13911 and GSE54129." (PMID 35186032, 2022).
cancer (continued). "By analyzing the expression profile of GC patients in the open online database, we found that the expression level of THBS2 in GC tissues was significantly higher than that in cancer-adjacent tissues." (PMID 35186032, 2022). "We further analyzed the mRNA expression of THBS2 in the ONCOMINE database to explore pan-cancer THBS2 expression." (PMID 35701829, 2022). "We performed a pan-cancer analysis of THBS2 expression in 33 tumors, and we found that THBS2 expression was strongly correlated with prognosis in PAAD and STAD." (PMID 35701829, 2022). "We used TIMER2 to analyze RNA sequencing data from the TCGA database and evaluate pan-cancer THBS2 expression." (PMID 35701829, 2022). "The results showed that the THBS2 mRNA expression level was higher in GC than in cancer-adjacent tissues (p < 0.001)." (PMID 35186032, 2022). "We further revealed the potential functions of THBS2+ CAFs, indicating that this subset possesses a potential capacity to modulate the cancer cells and, in particular, TME." (PMID 35547750, 2022). "We recently observed THBS2 upregulated in both cancer cells and stromal cells in dCCA specimens using mass spectrometry and immunohistochemistry." (PMID 34319497, 2022). "There was a significant difference in THBS2 expression between GC tissues and cancer-adjacent tissues (P < 0.001)." (PMID 35186032, 2022). "Immunohistochemistry (IHC) analysis demonstrated that THBS2 was detectable in cancer cells but prominently in peritumoral stromal cells." (PMID 35547750, 2022). "A clinical study of patients with cancer in China has found significant heterogeneity in the distribution of serum THBS2 in diverse types of cancer compared with healthy control individuals." (PMID 35701829, 2022). "Given that we identified a relationship between THBS2 expression and immune infiltration, we further analyzed correlations between THBS2 expression and 48 common immune checkpoint genes in 33 cancers." (PMID 35701829, 2022). "Since then, many research results were published connecting one of the genes COL11A1, INHBA, THBS2 with poor prognosis, invasiveness, metastasis, or resistance to therapy, in various cancer types." (PMID 34283835, 2021). "Specifically, a COL11A1/INHBA/THBS2-expressing gene signature was found to be present only after a particular staging threshold, different in each cancer type, was reached." (PMID 34283835, 2021). "MYC, SOX2, JUN, or ARNT was significantly correlated with THBS2 in most cancers, including COAD and PAAD." (PMID 34804159, 2021). "Our current study reveals a critical role for the chemotherapy‐enriched CD133 expressing cells that preferentially secrete less ECM‐modifying enzyme THBS2 to promote aggressive cancer and stemness properties in HCC." (PMID 33717837, 2021). "Particularly, THBS1 and THBS2 have an active effect on the EMT pathway in more than half of cancer types." (PMID 34804159, 2021). "Using the TCGA PanCancerAtlas for Mutual Exclusivity analysis of pan-cancer mutations, we uncovered cooccurrence relationships of THBS2, THBS4, and THBS5 with THBS1; THBS4, THBS3, and THBS5 with THBS2; and THBS3 and THBS4 with THBS5." (PMID 34804159, 2021). "We mainly found that THBS1, THBS2, and THBS3 are dysregulated in various cancers, and their expression level is associated with the prognosis of patients." (PMID 34804159, 2021). "Thrombospondin-2 (THBS2) is a matricellular protein with antiangiogenic activity, which can modulate extracellular matrix assembly, and correlates with cancer metastasis." (PMID 33777808, 2021). "In summary, we analyzed the prognostic landscape of THBS2 in CRC across multiple databases, explored the correlation between THBS2 expression and immune infiltration, and finally identified the THBS2 binding proteins and correlated genes in cancer." (PMID 34471634, 2021). "Consistently, wound-healing assay also suggested that knockdown of THBS2 attenuated cancer cell migration." (PMID 34804159, 2021).
cancer (continued). "Across the 18 cancers in their study, certain proteins stood out as pan-cancer markers such as THBS2, VCAN, SRRT, and TNC." (PMID 39698114, 2020). "COL6A3, COL8A1, CDH11, and CXCL12 were not expressed in either PDAC tissues or normal tissues, and BGN and THBS2 were overexpressed in both cancer and normal tissues." (PMID 33282565, 2020). "Studies in breast cancer models of lung metastasis have identified that cancer cells with high AXL expression also highly express thrombospondin-2 and this drives TGFβ1-dependent lung colonization." (PMID 33014869, 2020). "On the other hand, the expression profile of another subgroup A member, THBS2, is variable in different types of cancers." (PMID 27513329, 2016). "Based on the data on gene summary views (neoplastic vs. normal tissue), THBS2 was significantly up-regulated in 11 of 20 common cancers." (PMID 27513329, 2016). "This is further supported by other genes that correlated closely in many cancer forms such as FAP, PDGFRB, THBS2 and VCAN which are also markers for matrix-producing cells and in some cases also for cancer-associated fibroblasts." (PMID 27809802, 2016). "Module III represents CAFs expressing COL1A1, COL1A2, and COL3A1 enriched in the cancer regions, whereas module IV identifies a subset known as myofibroblasts (myCAFs) (COL12A1, THBS2) that mainly contribute to extracellular matrix remodeling and growth and metastasis of cancer cells." (PMID 40033360, 2025). "THBS2 in many cancers is a double-edged sword, exerting oncogenic and anti-angiogenic effects." (PMID 39857742, 2025). "The role of THBS2 in ectopic epithelial cells might differ from that of cancer cells; lower expression of THBS2 under PNX-14 stimulation may cause increased cell viability, metabolism, and migration." (PMID 39857742, 2025). "In this study, overexpression of miR-664a-3p could decrease the expression level of THBS2, which may lead to angiogenesis and cancer progression." (PMID 38035445, 2024). "Collectively, THBS2, related to angiogenesis and cancer progression, may be a potential target gene of miR-664a-3p." (PMID 38035445, 2024). "Moreover, THBS2 demonstrated the ability to alter the biological characteristics of cancer cells to regulate the progression of cancer." (PMID 36609437, 2023). "Additionally, reducing THBS2 levels was found to diminish the ability of cancer cells to activate pulmonary fibroblasts." (PMID 37834250, 2023). "THBS2 has been reported to be dysregulated in numerous cancers, including NSCLC." (PMID 36609437, 2023). "Along this line, two other studies have suggested that integrating the plasma levels of CA 19-9 and thrombospondin-2 could distinguish malignant periampullary tumors from benign conditions." (PMID 36900245, 2023). "Many studies have found that THBS2 is highly expressed in different cancers, including RCC." (PMID 38110984, 2023). "In addition, among these top interactions, we found THBS2/THBS3 secreted by myCAF2 targeting CD47 of cancer cells." (PMID 36352420, 2022). "Furthermore, THBS2 was closely associated with various ECM and immune proteins and the expression of immune checkpoint markers in various cancer types." (PMID 35701829, 2022). "Firstly, the THBS2 expression level in GC was significantly higher than that in para-cancer tissues, and THBS2 may be a potential biomarker for GC diagnosis." (PMID 35186032, 2022). "Due to its role in the ECM, THBS2 augments cancer cell migration." (PMID 35159353, 2022). "Material and Methods: The differential expression levels of THBS2 in the GC and cancer-adjacent tissues were identified using the TCGA databases and verified using real-time polymerase chain reaction (PCR), immunohistochemical staining and two datasets from Gene Expression Omnibus (GEO)." (PMID 35186032, 2022).
cancer (continued). "Data on THBS2 expression in cancers and normal tissues were downloaded from the Genotype-Tissue Expression portal and UCSC Xena visual exploration tool and analyzed using the ONCOMINE database, Perl programming language, and Gene Expression Profiling and Interactive Analyses vision 2 webserver." (PMID 35701829, 2022). "Naturally, the expression of THBS2 in a patient with cancer increases." (PMID 36415513, 2022). "Many studies had suggested that knockdown of THBS2 could promote cancer cell metastasis, proliferation, and angiogenesis." (PMID 35415249, 2022). "Except for DLBC, increased THBS2 expression negatively impacted PFI in these cancer types." (PMID 35701829, 2022). "THBS2 was highly expressed in different cancers including CRC." (PMID 34471634, 2021). "Depletion of THBS2 significantly inhibits cancer cell migration and attenuates EMT phenotypes." (PMID 34804159, 2021). "Next, we explored the ability of THBS2 to regulate functional cancer stemness properties." (PMID 33717837, 2021). "The high expression of THBS2 was correlated with worse survival in fourteen types of cancers." (PMID 34804159, 2021). "In multiple malignancies, THBS2 is tight correlated with progression and prognosis of cancers." (PMID 34659407, 2021). "In line with this hypothesis, it was identified that CAFs exhibiting the “metastasis signature” composed of COL11A1, INHBA (inhibin beta A), THBS2 (thrombospondin 2), originate from adipocytes when the cancer metastasizes to a fat-rich microenvironment." (PMID 33668097, 2021). "Overexpression of THBS2 predicts short overall survival in these three cancers." (PMID 34804159, 2021). "Moreover, cancer stem carcinoma cell-derived EVs transport miR-221-3p from cancer cells to vessel endothelial cells and promote angiogenesis by downregulating the protein THBS2." (PMID 33467651, 2021). "These genes showed positive correlation with THBS2 across most cancer types in TIMER 2.0 database." (PMID 34471634, 2021). "Finally, we also selected THBS2 as a representative to study its potential roles in cancer metastasis and EMT by functional experiments." (PMID 34804159, 2021). "Subsequently, we further conducted the ELISA assay and found the load of CA19-9 in serum of patients diagnosed with EGC was higher than that in EGT as well as in HC, which illustrated that cancer tissues were likely to produce more THBS2 in serum in accordance with former research studies." (PMID 34659407, 2021). "Thrombospondin 2 (THBS2) acts as oncogenic or tumor suppressive gene in diverse cancers." (PMID 34471634, 2021). "Upregulating THBS2 in cancer tissues is correlated to inhibit progression of tumors sometimes." (PMID 34659407, 2021). "Compared with THBS1, researches on THBS2 are limited in human cancer and especially rare in CRC." (PMID 33244454, 2020). "THBS2 is a thrombospondin family protein and negatively regulates angiogenesis in cancer." (PMID 31612481, 2020). "On one hand, THBS2 is mostly described as an anti-angiogenic, anti-metastatic factor in cancer." (PMID 29176937, 2017). "As the member of THBS family, THBS2 plays an important role in cancer progression." (PMID 29348878, 2017). "The findings suggest that THBS2 and its coexpressing genes may play a significant role in biological processes during cancer progression." (PMID 27513329, 2016). "Above results suggested that THBS2 was a cancer-related gene in CRC." (PMID 27632935, 2016). "Overall, the results suggest that the cluster of genes that was coexpressed with THBS2 may promote cancer progression through the induction of biological processes and immune modulation." (PMID 27513329, 2016). "Notably, THBS1 and THBS2 are special in this family for their type I repeats and both of them are mainly shown as inhibitors of angiogenesis, one key part of cancer research." (PMID 25262009, 2014). "Evidence has also suggested that THBS2 could play vital roles in cancer progression and metastasis." (PMID 36405394, 2022).
cancer (continued). "Importantly, depletion of THBS2 significantly decreased the migration of cancer cells." (PMID 34804159, 2021). "In addition, serum THBS2 has been regarded as a valuable clinical marker for various cancers." (PMID 34659407, 2021). "Here, we deepened the study on nine of them (ASS1, EIF4G1, GALNT7, GLUT1, IGF2BP3 (IMP3), ITGA4, RAN, SOD1, and THBS2) to ascertain whether they are truly mesothelial cancer driver genes (CDGs) or genes overexpressed in an adaptive response to the tumoral progression (“passenger genes”)." (PMID 32659970, 2020). "In addition, investigation of microarray datasets derived from 98 colorectal patients and 50 healthy volunteers revealed that THBS2 mRNA is increased not only in the stage II tumors but also in normal adjacent mucosa of cancer patients compared to healthy control individuals." (PMID 29176937, 2017). "Exosomal ALPPL2 and THBS2 distinguished non-cancer cases from PDAC with high accuracy; area under the curve (AUC) values = 0.983, 0.993, and 0.983 for ALPPL2, THBS2, and the dual marker combination, respectively." (PMID 40897818, 2025). "Eighteen overlapping DEGs were identified between the two CRC cell lines, four of which are closely related to cancer progression, namely FGF1, THBS2, DAPK2, and GSTM2." (PMID 41039172, 2025). "Our findings revealed that cancer had lower expression of THBS1, THBS3, and THBS4 compared to normal tissue, whereas the expression of THBS2 was higher." (PMID 38827236, 2024). "In particular, THBS2 was remarkably positively correlated with CAF activation and EMT at the pan-cancer level, confirmed by scRNA-seq and ST." (PMID 39732719, 2024). "Here, by integrating with multi-omics data, we provided evidence that THBS2 derived from specific subsets of CAFs, defined as THBS2 + CAFs, correlated with dismal prognosis and EMT activity across various cancer types." (PMID 39732719, 2024). "Collagens, MIF, MDK, APP, and laminin were detected as the most significant signaling, and the top ligand-receptor interactions THBS2/THBS3 (CAFs)—CD47 (cancer cells), MDK (CAFs)—NCL/SDC2/SDC4 (cancer cells) as potential therapeutic targets." (PMID 36352420, 2022). "However, the exact role of THBS2 in human cancer remains unknown." (PMID 35701829, 2022). "Secondly, the THBS2 expression in 375 STAD samples and 32 para-cancer samples in the TCGA was compared." (PMID 35186032, 2022). "The expression of THBS2 influenced DSS in ACC, KIRC, KIRP, LGG, MESO, PAAD, and UVM among 32 types of cancer." (PMID 35701829, 2022). "The high level of THBS2 in the plasma of PDAC patients has been demonstrated, and resectable PDAC stage I cancer and advanced stage III/IV can differ with the concentration of THBS2 in plasma." (PMID 36415513, 2022). "Additional research is needed to elucidate the expression pattern of THBS2 in other subtypes of CCA and across carcinomas of different origins." (PMID 34319497, 2022). "EV biomarkers of note include the stromal proteins versican (VCAN) and thrombospondin 2 (TSP2), which were part of a highly accurate (~90% sensitivity/95% specificity) 16 EV pan-cancer signature." (PMID 34298706, 2021). "Our histopathological evidence has shown that COL12A1 and FN1 are expressed from stromal cells, THBS2, and VCAN from stromal and cancer cells, while ITGA2, LAMB3, and LAMC2 are expressed solely from the cancer cells." (PMID 34007003, 2021). "We found that inhibition of THBS2 significantly attenuated cancer cell EMT and decreased cancer cell migration." (PMID 34804159, 2021). "Recent cancer studies have found that the thrombospondin (THBS) family, including THBS1, THBS2, THBS3, THBS4, and THBS5, play vital roles in the development and progression of human cancers." (PMID 34804159, 2021). "Among these proteins, the overexpression of MMP14, ITGA2, THBS2, COL1A1, COL3A1, COL11A1 and COL6A3 has been experimentally confirmed in PDAC, while that of COL12A1 and COL5A2 has been shown in other types of cancer." (PMID 34094925, 2021).